SRSF1 (serine and arginine rich splicing factor 1)
Diseases named in the same sentence as SRSF1 in open-access papers (continued):
Sharing a sentence is not in itself a finding about the gene and the disease.
glioblastoma (35 papers, 2015 to 2025). The most malignant astrocytic tumor (WHO grade IV). "In glioblastoma cells, positive cell migration regulator splicing factor 1 (SRSF1) exhibits multiple binding sites for circSMARCA5." (PMID 39239069, 2024). "The positive cell migration regulator splicing factor 1 (SRSF1) is expressed at high levels in glioblastoma cells, and it exhibits multiple binding sites for circSMARCA5." (PMID 37122733, 2023). "More recently, it has been shown that the GAUGAA motif (on circSMARCA5/ciTRAN) is recognized by the SRSF1 protein, and this interaction determines the aggressive nature of glioblastoma multiforme." (PMID 37672576, 2023). "CircSMARCA5 acts as the sponge for SRSF1 in glioblastoma multiforme (GBM), regulates the splicing of VEGFA, and affects angiogenesis." (PMID 35806027, 2022). "A decrease in the circSMARCA5 expression leads to upregulation of the circSMARCA5-associated RBP serine- and arginine-rich splicing factor 1 (SRSF1), which promotes glioblastoma angiogenesis." (PMID 34449657, 2021). "Such as, UPF1 regulates the progression of glioblastoma cells by improving the stability of linc‐00313,33 SRSF1 stabilized lncRNA NEAT1 to regulate the cell cycle progression in glioma." (PMID 33128346, 2020). "Overexpressing circSMARCA5 in glioblastoma multiforme cells significantly decreases their migration via regulating the SRSF1/SRSF3/PTB axis." (PMID 30956729, 2019). "CircRNA SMARCA5 binds to SRSF1 protein to modulate VEGFA mRNA splicing in glioblastoma multiforme." (PMID 36800233, 2023). "Hsa_circ_0001445 could regulate VEGFA mRNA through binding to SRSF1 in glioblastoma, while in HCC, it sponged miR-17–3p and miR-181b-5p to induce the expression of TIMP3 in order to inhibit growth and metastasis." (PMID 34992634, 2021). "Hence, a decrease in circSMARCA5 in glioblastoma enhances cell migration and angiogenesis by upregulating SRSF1 expression through PTBP1 and VEGFA." (PMID 34449657, 2021). "Barbagallo and colleagues reported that circSMARCA5 regulated the interaction with SRSF1 and some related downstream effects on glioblastoma multiforme cell migration and angiogenic potential through in vitro and in silico characterization of its GAUGAA motif sequences." (PMID 34988221, 2021). "For instance, circSMARCA5 could regulate VEGFA mRNA splicing and angiogenesis through the binding of SRSF1 in glioblastoma multiforme." (PMID 34034688, 2021). "Additionally, current evidence shows that circRNA SMARCA5 (circ-SMARCA5) can bind to serine and arginine rich splicing factor 1 (SRSF1) to regulate VEGFA pathway in glioblastoma multiforme (GBM) cells." (PMID 31937318, 2020). "We next wanted to test if SRSF1 decoy oligonucleotides can inhibit glioblastoma growth in vivo." (PMID 30962446, 2019). "Furthermore, CircSMARCA5 could regulate angiogenesis in glioblastoma multiforme through the binding of SRSF1." (PMID 36065311, 2022). "We recently showed that circSMARCA5 is a tumor suppressor in glioblastoma multiforme (GBM) and acts as a decoy for Serine and Arginine Rich Splicing Factor 1 (SRSF1) through six predicted binding sites (BSs)." (PMID 33562358, 2021). "CircSMARCA5 inhibits glioblastoma multiforme (GBM) cell migration by sequestering serine and arginine rich splicing factor 1 (SRSF1) that enhances exon 4 skipping in SRSF3 pre-mRNA." (PMID 33317550, 2020). "We recently proposed that circSMARCA5 acts as sponge for the splicing factor Serine and Arginine Rich Splicing Factor 1 (SRSF1) in glioblastoma multiforme (GBM)." (PMID 30736462, 2019). "For instance, circSMARCA5 can act as a sponge for serine/arginine-rich splicing factor 1 (SRSF1) protein, regulating vascular endothelial growth factor (VEGFA) and thus affecting glioblastoma multiforme." (PMID 39796233, 2025). "SRSF1 regulates the expression of the tumorigenic tyrosine kinase receptor (RON) and is allied to shorter survival in glioblastoma patients." (PMID 39863145, 2025).
glioblastoma (continued). "In glioblastoma multiforme, circ-SMARCA5 functions as a sponge for the splicing factor serine and arginine rich splicing factor 1 (SRSF1) (GBM)." (PMID 35883576, 2022). "SRSF1 (serine/arginine-rich splicing factor 1) promotes proliferation and injury-induced neointima formation in vascular smooth muscle cells, and it could promote tumorigenesis through regulation of alternative splicing in colon cancer, glioblastoma, and other cancers." (PMID 35178295, 2022). "For example, circSMARCA5, a downregulated tumor suppressor in glioblastoma, binds with SRSF1 directly via the GAUGAA motif and acts as a decoy for the oncogenic SRSF1, resulting in the suppression of SRSF1-induced oncogenicity." (PMID 35059468, 2022). "The molecular characterization of circSMARCA5 has recently been published, a circular RNA has been found to be downregulated in WHO grade IV glioblastoma (GBM) biopsies with respect to normal brain parenchyma; it acts as a decoy for the oncogenic serine and arginine rich splicing factor 1 (SRSF1)." (PMID 33925821, 2021). "Treatment of glioblastoma cells with MA led to the inhibition of GSK3 kinase, resulting in the downregulation of SRSF1/5, PTPB1, and hnRNP with decreased levels of anti-apoptotic genes such as BCL2, BCL-xL, Survivin, MCL1, and BMI1 while increased in Anxa7, a tumor suppressor gene." (PMID 39863145, 2025). "For instance, in glioblastoma, tumorigenic RBP SRSF1 was found to bind to circSMARCA5 at multiple sites, with this circRNA functioning as a tumor suppressor, regulating the activity of SRSF1/SRSF3/PTB axis and preventing tumor angiogenesis and migration." (PMID 37835380, 2023). "In addition, the binding of circSMARCA5 to SRSF1 also regulated the mRNA splicing of VEGFA, thereby preventing tumor angiogenesis, and suppressing the development of glioblastoma." (PMID 36231036, 2022). "Interestingly, in glioblastoma (GBM) cells, hnRNP A2/B1 showed splicing effects similar to the proto-oncogenic SR protein SRSF1." (PMID 33261131, 2020).
glioma (26 papers, 2014 to 2025). A benign or malignant brain and spinal cord tumor that arises from glial cells (astrocytes, oligodendrocytes, ependymal cells). "SRSF1 has also been found to be overexpressed in brain glioblastoma and to be potentially used as a diagnostic marker of gliomas." (PMID 34768829, 2021). "Since up-regulation of SRSF1 associates with tumor progression and poor prognosis in gliomas, these observations suggest that the SRSF1-guided splicing switch contributes to malignancy by fueling proliferative pathways." (PMID 31861467, 2019). "In VM, SRSF1 stabilised circCMTM3 upon its entry into differentiated glioma cells via exosomes, preventing its degradation." (PMID 40869298, 2025). "The high expression of SRSF1 in glioma patients correlated with adverse unfavorable clinical features." (PMID 37063420, 2023). "For example, the splice switch of MYO1B directly regulated by SRSF1 increased the carcinogenic potential of glioma cells through the PDK1/AKT and PAK/LIMK pathways." (PMID 37667311, 2023). "We found SRSF1 also interacts with miR-7 in lower grade glioma—more specifically with miR-7-2-3p (P ≈ 9.22e−8 for setting ALLT)." (PMID 37705830, 2023). "The positive feedback loop of GSCAR/DHX9-IGF2BP2/SOX2 distinguishes glioma stem cells from other glioma tumor cells regulated by the GSCAR/miR-6760-5p/ SRSF1 axis." (PMID 37063420, 2023). "In line with our findings, previous studies have shown that SRSF1 was increased in gliomas, which promoted gliomagenesis via guided alternative splicing of the MYO1B gene, leading to activation of PDK1/AKT and PAK/LIMK signaling pathways." (PMID 37063420, 2023). "SRSF1 expression was also correlated with other parameters of increased malignancy of gliomas, such as cell migration, MVD and autophagy activation." (PMID 33925821, 2021). "SRSF1 has also been identified as a potential oncogene that is overexpressed in several cancers including glioma." (PMID 33858489, 2021). "CircSMARCA5 affects the malignant behavior of glioma by regulating serine and arginine rich splicing factor 1 (SRSF1)/SRSF3/PTB." (PMID 34249673, 2021). "Further studies with a larger cohort of cases and a wider autophagic immunohistochemical panel are required to better clarify the potential correlation between SRSF1 and autophagy in gliomas." (PMID 33925821, 2021). "We performed orthotopic xenografts to confirm the effects of the SRSF1/circATP5B/miR-185-5p/HOXB5 axis in glioma tumorigenesis in vivo." (PMID 33858489, 2021). "We also certified that there were significant positive correlations between HOXB5 and SRSF1 expression in clinical glioma specimens." (PMID 33858489, 2021). "Serine/arginine-rich splicing factor 1 (SRSF1) is an RBP that is upregulated in glioma and plays an important role by regulating splicing, RNA stability, and nuclear export." (PMID 34395233, 2021). "In summary, our results suggested that the SRSF1/circATP5B/miR-185-5p/HOXB5 axis regulates glioma tumorigenesis and proliferation in vivo." (PMID 33858489, 2021). "By RNA-sequencing (RNA-seq) they discovered that the knockdown of SRSF1 in two glioma cell lines resulted not only in differential expression of mRNAs but also of ncRNAs." (PMID 32340118, 2020). "Most specifically, based on REMBRANDT data, SRSF1 mRNA was significantly upregulated in all glioma grades with respect to normal brain (p-value < 0.0001, ANOVA test), while VEGFA was significantly upregulated specifically in GBM (p-value < 0.0001, ANOVA test)." (PMID 30736462, 2019). "As a well-characterized oncoprotein, SRSF1 promotes glioma-cell migration." (PMID 40723354, 2025). "Furthermore, SRSF1 promotes cell proliferation, survival, and invasion in glioma tissues and cell lines by specifically switching the AS of myosin IB (MYO1B)." (PMID 36882745, 2023). "Similarly, the serine/arginine-rich splicing factor 1 (SRSF1) plays a positive role on the regulation of lncRNA NEAT1 in gliomas." (PMID 34796209, 2021).
glioma (continued). "Therefore, the SRSF1/circATP5B/miR-185-5p/HOXB5 feedback loop is considered to be involved in glioma proliferation." (PMID 33858489, 2021). "SRSF1 has been recently characterized as being functionally involved in gliomagenesis and it has been found that SRSF1 is increased in glioma tissues and its increased immunohistochemical expression among adult diffuse astrocytomas is positively correlated with histological grade." (PMID 33925821, 2021). "In addition, Pearson’s correlation analyses among clinical glioma specimens showed significant positive correlations between HOXB5 and SRSF1 expression in each WHO grade glioma and among the total glioma samples." (PMID 33858489, 2021). "Finally, we conclude that the SRSF1/circATP5B/miR-185-5p/HOXB5 feedback loop is involved in glioma tumorigenesis and proliferation." (PMID 33858489, 2021). "However, few of splicing factors such as PTBP1 (polypyrimidine tract binding protein), SRSF1 (SR protein), and hnRNPs are found to be aberrantly overexpressed in breast cancer, gliomas, and so forth." (PMID 24550987, 2014). "Additionally, SRSF3 is expressed at higher levels in glioma, and it may act as a positive regulator of SRSF1‐dependent glioma cell migration." (PMID 39239069, 2024). "In addition, we confirmed that SRSF1 knockdown inhibited glioma cell growth and migration and showed that SRSF1 overexpression could reverse GSCAR knockdown-reduced cell growth and migration abilities." (PMID 37063420, 2023). "Moreover, higher levels of splicing factor 3 (SRSF3) expression are observed in glioma and it has been speculated to function as a positive regulator of SRSF1-dependent glioma cell migratory activity." (PMID 37122733, 2023). "This feedback loop between SRSF1, circCMTM3, and STAT5A promoted the VM formation, proliferation, invasion, and migration of glioma cells by upregulating CHI3L2." (PMID 40869298, 2025). "We tested the immunohistochemical expression of SRSF1 in a cohort of patients affected by GBM and other glial neoplasms, including 21 oligodendrogliomas, 15 ependymomas, 15 Pas, 5 SEGAs and 4 PXAs." (PMID 33925821, 2021). "SRSF1, a splicing factor and a type of RBP, has been reported to be overexpressed in several cancers including glioma, and participates in diverse biological functions, including translation, nonsense-mediated RNA decay, and RNA transport." (PMID 33858489, 2021). "Serine/arginine-rich splicing factor 1 (SRSF1) is another RBP that is commonly overexpressed in cancer and that exerts oncogenic effects, for example in glioma, by regulating splicing, RNA stability, and nuclear export." (PMID 32340118, 2020). "Previous studies have demonstrated that most SRSFs were extensively dysregulated with oncogenic roles through regulating the AS of various cancer-related genes in many cancers such as lung (SRSF1, SRSF5), breast (SRSF3), colon (SRSF1, SRSF10), liver cancers (SRSF2), and glioma (SRSF1, SRSF3)." (PMID 37558679, 2023). "The aim of this study is to evaluate the immunohistochemical expression of the SRSF1 protein in a series of astrocytic and non-astrocytic adult gliomas, emphasizing its potential use in the differential diagnosis of these neuropathological entities." (PMID 33925821, 2021). "Nevertheless, we investigated both the role of SRSF1 as a potential poor prognostic factor in GBM patients and its oncogenic function through correlations with other predictors of glioma malignant behavior, including cell migration, blood vascular microvessel density (MVD) and autophagy." (PMID 33925821, 2021). "Moreover, Further studies revealed that SRSF1-mediated splicing of the MYO1B increased the potential of proliferation, and metastasis in glioma cells by regulating the PDK1/AKT and PAK/LIMK pathway." (PMID 32760211, 2020).
glioma (continued). "A study showed that has-circ-0001445 (circSMARCA5) substantially decreased in the glioma tissue and indirectly regulates the expression of serine/arginine-rich splicing factor 3 (SRSF3) isoforms by interacting with serine and arginine-rich splicing factor 1(SRSF1)." (PMID 40723354, 2025). "However, miR-6760-5p or SRSF1 was not increased in GSC-like cells compared to parental cells and was also not positively associated with the expression of glioma stem cell biomarkers." (PMID 37063420, 2023). "Therefore, we decided to decipher the potential mechanism by which the GSCAR/miR-6760-5p/SRSF1 axis and GSCAR/DHX9-IGF2BP2/SOX2 feedback loop promote glioma progression, which may provide new therapeutic targets for glioma in the future." (PMID 37063420, 2023). "Interestingly, GSCAR was identified to increase the stemness of glioma stem cells independent of the GSCAR/miR-6760-5p/SRSF1 axis." (PMID 37063420, 2023). "Therefore, our study found a novel feedback loop involving the SRSF1/circATP5B/miR-185-5p/HOXB5 axis that regulates the proliferation of GSCs and may provide a novel target for glioma therapy." (PMID 33858489, 2021). "The findings suggest a negative correlation between circSMARCA5 expression and glioma progression, highlighting its potential role as a tumor suppressor through RBP SRSF1 sequestration." (PMID 40723354, 2025). "We revealed that only SRSF1, but not IGFBP2 and EMP3, was markedly reduced by miR-6760-5p mimics but increased by miR-6760-5p inhibitors in glioma tumor cells, suggesting that SRSF1 is the direct target of miR-6760-5p." (PMID 37063420, 2023).
gastric cancer (23 papers, 2008 to 2026). A primary or metastatic malignant neoplasm involving the stomach. "For instance, our previous experimental study showed that MALAT1 regulated the ASF, SRSF1 (SF2) in gastric cancer cells." (PMID 32760422, 2020). "It was previously shown in mammary and gastric carcinoma cell lines that overexpression of SRSF1 activates the epithelial to mesenchymal transition (EMT) and induces a more invasive phenotype." (PMID 23071587, 2012). "Moreover, CCL21-mediated activation of the MALAT1/SRSF1/mTOR axis underpins the development of gastric carcinoma." (PMID 34421979, 2021). "Further experiments are needed to investigate whether RBM4 interacts directly with Bcl-x and SRSF1 or binds to other splicing factors to suppress tumor progression in vitro and in mouse models of gastric cancer." (PMID 27324405, 2016). "Recent studies have shown that MALAT1 enhances the expression of serine-rich arginine splicing factor 1 (SRSF1) and activates the mammalian rapamycin target (mTOR) signaling pathway to promote the formation of gastric cancer (GC) and hepatocellular carcinoma (HCC)." (PMID 35208500, 2022). "The experiments revealed a reduced expression of SRSF1 and SRSF2 in pancreatic, kidney, colorectal, and stomach cancer cell lines as well as in cancer tissues — SRSF2 was downregulated in stomach tumors, while SRSF1 was reduced in all types of tested tumors." (PMID 27019673, 2016). "We checked the relationship between SRSF1 and MALAT1 in gastric cancer cell lines (data not shown)." (PMID 28077118, 2017).
hepatocellular carcinoma (22 papers, 2012 to 2025). A malignant tumor that arises from hepatocytes. "For example, SRSF1 overexpression was reported to increase tumor invasion and metastasis in hepatocellular carcinoma." (PMID 37206090, 2023). "In summary, our results provide experimental evidence that SRA1 exon 3 inclusion is up regulated by SRSF1 to promote tumor invasion and metastasis in hepatocellular carcinoma." (PMID 34011971, 2021). "For example, lncRNA MALAT1 promoted hepatocellular carcinoma development by regulating SRSF1 and activating mTOR signaling." (PMID 34240756, 2021). "In this study, We found that SRSF1 regulates the alternative splicing of SRA1 to promote the migration of hepatocellular carcinoma cells." (PMID 34011971, 2021). "SRSF1 has been identified as an oncoprotein involved in many cancers, including those of the lung, colon, breast, as well as in hepatocellular carcinoma." (PMID 22839530, 2012). "Interestingly, the overexpression of SRA1-L reversed the inhibitory effect of down-regulated SRSF1 on lung metastasis of hepatocellular carcinoma cells." (PMID 34011971, 2021). "In addition, compared with the control group, the inhibitory effect of sh-SRSF1 + SRA1-S on lung metastasis of hepatocellular carcinoma cells was stronger in the experimental group." (PMID 34011971, 2021). "For instance, in hepatocellular carcinoma (HCC), SRSF1 can enhance KLF6 alternative splicing through the phosphoinositide 3-kinase (PI3K)/Akt signaling pathway, generating three splice variants that expedite tumor progression and metastasis." (PMID 38735973, 2024). "Overexpression of either SRSF1 or SRA1-L promotes migration and invasion of hepatocellular carcinoma cells by enhancing the expression of CD44." (PMID 40129567, 2025). "In hepatocellular carcinoma (HCC), SRSF1 promotes tumor infiltration and subsequent metastasis by regulating the alternative splicing of SRA1." (PMID 39336772, 2024). "And overexpression of SRSF1 and knockout of SRA1-L reduced the invasion of hepatoma cells, compared with HepG2 cells with overexpression of SRSF1 alone." (PMID 34011971, 2021). "Accumulating evidence has revealed that MALAT1 enhances the expression of serine arginine-rich splicing factor 1 (SRSF1) and activates the mammalian target of rapamycin (mTOR) signaling pathway in hepatocellular carcinoma (HCC)." (PMID 34001131, 2021). "Also, western-blot results indicate that the expression of SRSF1 in HCCLM3 cells was significantly higher than that in normal LO2 cells and low-transformed hepatoma cells, HepG2 and Huh-7." (PMID 34011971, 2021). "In this study, we found that SRSF1 can regulate the alternative splicing of SRA1 in hepatocellular carcinoma cells, but the specific mechanism is not clear." (PMID 34011971, 2021). "In hepatocellular carcinoma (HCC), MALAT1-upregulated SRSF1 enhances the isoforms of the antiapoptotic gene BIM and the oncogenes S6K1 and TEAD1, leading to cancer cell proliferation, survival, and tumorigenesis." (PMID 32967226, 2020).